IL6 (interleukin 6)
Diseases named in the same sentence as IL6 in open-access papers (continued):
Sharing a sentence is not in itself a finding about the gene and the disease.
COVID-19 (continued). "Hyponatremia is caused by various mechanisms, including the non-osmotic release of vasopressin induced by interleukin 6, the levels of which are increased in COVID-19 patients and inversely related to hyponatremia." (PMID 34521357, 2021). "Colchicine has been shown to effectively suppress interleukin IL-1b, IL-18 and IL-6 in patients with acute coronary syndrome and is now being trialed in COVID-19 ARDS, albeit it also has very significant side effects." (PMID 33465050, 2021). "Subsequently, to further determine whether SARS-CoV-2 infection in AAV/hACE2 mice model could also induce proinflammatory mediators as shown in severe COVID-19 patients, RNA levels of TNF-α, IL-1β, IL-6, CCL2, and CXCL10 in mice lung homogenates were measured." (PMID 34379705, 2021). "Levels of IL-6 and TNF-α increased significantly in the acute phase of SARS-CoV-2 infection, in good agreement with previous observations showing elevated IL-6 in the setting of severe COVID-19." (PMID 34884175, 2021). "This information becomes more significant in patients with COVID-19, wherein increased levels of TNF-alpha and IL-6 may directly decrease albumin production and lead to hypoalbuminemia." (PMID 34683480, 2021). "In COVID-19 patients, the cytokine storm was mediated by high-levels of proinflammatory cytokines, and the severe cases showed significantly higher cytokines and chemokines, such as TNF-α, IL-6, and IL-10 expressed." (PMID 34439967, 2021). "RNA sequencing analysis of cell and animal models of SARS-CoV-2 infection, blood, lung, and airway biopsies from COVID-19 patients showed inflammatory responses characterized by low levels of type I and III IFNs, increased interleukin-6 (IL-6), and a variety of chemokines." (PMID 34531741, 2021). "Additionally, mTOR-I when given at the early onset of the cytokine storm phase can hinder the IL-6 pathway and NLRP3 inflammasome-dependent release of IL-1β, thus preventing the progression to severe forms of COVID-19." (PMID 34497515, 2021). "The predictive values of IL-6 for differentiating four subpopulations of COVID-19 patients, including non-survivors, critical subtype, severe group (including both critical and severe subtypes), and severe subtype, from the non-severe group were compared." (PMID 33693017, 2021). "The avoidance of hypercytokinemia is a pivotal therapeutic aim in COVID-19, similar to AID, and cytokine targeting agents, such as anti-IL-1 treatment, anti-IL-6 treatment or Janus kinase inhibitors may be promising." (PMID 33562758, 2021). "Levels of IL-6 and TNF both independently predict COVID-19 disease severity and mortality and may be important therapeutic targets." (PMID 34341776, 2021). "An inverse relationship between IL-6 and GHS levels has been reported in COVID-19 patients." (PMID 34360751, 2021). "In COVID-19 patients, increased plasma pro-inflammatory cytokines such as IL-1, IL-6, IL-8, and TNF-α levels have been reported that may contribute to CRS onset in severe COVID-19 patients." (PMID 34176095, 2021). "Referring to Pal and Bhadada, DM is also a pro-inflammatory state, and COVID-19 patients with DM showed significantly higher serum levels of interleukin-6 (IL-6), C-reactive protein and ferritin than those without DM." (PMID 34416856, 2021). "Sixty-eight percent of diabetic patients with COVID-19 had increased values of IL-6 (40.7%; p =0.001), and 38.7% of non-DM patients presented these modifications." (PMID 34201473, 2021). "Patients with MAFLD and elevated IL-6 levels had a significantly higher proportion of severe COVID-19 than those with elevated IL-6 levels but without MAFLD (47.83% vs. 19.57%, p = 0.015)." (PMID 33763027, 2021). "We found that statins may be effective by ameliorating endothelial dysfunction triggered by cytokine storm cytokines/chemokines (IL-6, TNF-α, IL-1β, CCL2, interferons, and related factors) released from COVID-19 patients." (PMID 34253708, 2021).
COVID-19 (continued). "Among non-MAFLD patients, patients with elevated IL-6 levels appeared to have a higher proportion of severe COVID-19 than those with normal IL-6 levels but the effect was not statistically significant (19.57% vs. 13.33%, p = 0.360)." (PMID 33763027, 2021). "D-dimer in COVID-19 patients was a significantly positively correlated with CRP and IL-6." (PMID 34222271, 2021). "Some authors, unlike our reports, stated that pediatric COVID-19 cases with mild clinical presentation had IL-6 levels within a normal range or rarely elevated." (PMID 34578450, 2021). "Plasma gp96 levels that were positively correlated with interleukin-6 (IL-6) levels were significantly elevated in COVID-19 patients admitted to the hospital but not in non-COVID-19 patients with less severe respiratory impairment." (PMID 34817280, 2021). "Our multivariate model showed that COVID-19 was related to increased expression levels of TNF-α, IL-1β, IL-6, IL-8, IL-12B, and IL-10 (P < 0.05), and that leprosy simultaneously enhanced the levels of IL-6 (P = 0.046) and IL-12B (P = 0.020)." (PMID 33819170, 2021). "Overexpression of IL6, for example, as reported in several COVID-19 studies, did not provide an effective clinical signal for COVID-19 treatment in an initial clinical trial (COVACTA)." (PMID 35145507, 2021). "In fact, COVID-19 presents a unique and inappropriate inflammatory response, defined by decreased levels of type I and III interferons and increased production of IL-6 and chemokines (that attract/recruit T cells, NK cells, monocytes and/or macrophages and neutrophils)." (PMID 33916917, 2021). "In this study, PaO2/FiO2 was an independent predictor of COVID-19 death irrespective of considering IL-6." (PMID 33795768, 2021). "The plasma from severe COVID-19 patients similarly exhibited increased IL-6, IL-10, and MCP-1 levels, but these levels were not as high as those in patients with CRS from other causes such as sepsis and burns." (PMID 34867988, 2021). "It was then determined that despite systemic and placental increases in inflammation markers, such as IL-1β and IL-6, little to no symptoms of COVID-19 presented." (PMID 34564316, 2021). "There is emerging evidence of cytokine over-production, in particular IL-6 and IL-10, as part of immunopathogenesis within COVID-19; however, drivers of these observed changes are still not fully understood." (PMID 33493185, 2021). "To date, only IL-6 levels have been studied in COVID-19 patients with and without headache, in retrospective studies with contradictory results." (PMID 34088273, 2021). "Among routine markers of inflammation, PCT and TNF-α, but not CRP, IL-6 or ferritin, were higher in COVID-19 patients on MV compared to those not on MV." (PMID 33058027, 2021). "Likewise, the combined ratio between IL-6 and the T CD8 cell count improves mortality prediction in COVID-19 patients, performing better than other clinical prediction tools, such as the CURB-65 score." (PMID 34683480, 2021). "A 2.9-fold increase in IL-6 concentration has been found in COVID-19 patients, compared with patients with no complications, and IL-6 has been seen to be higher in nonsurvivors." (PMID 33921113, 2021). "However, IL-6 levels along with other laboratory indicators, like CRP, prothrombin time (PT), and D-dimer, provide a more accurate assessment of complications in COVID-19 patients." (PMID 35126355, 2021). "An analysis of 191 in-patients at two Wuhan hospitals revealed that blood concentrations of IL-6 differed between patients who did and did not recover from COVID-19." (PMID 33688554, 2021).
COVID-19 (continued). "Indeed, among the deceased patient of COVID-19, the level of TNF-α, IL-6, IL-1β, and IL-8, were the highest when compared to recovered cases." (PMID 33632295, 2021). "Clinically, COVID-19 patients diagnosed with acute stroke exhibited higher serum IL-6 than patients not diagnosed with acute stroke, starting at 3 days post-admission." (PMID 34944606, 2021). "Elevated inflammatory cytokines such as interleukin-6 (IL-6), granulocyte colony-stimulating factor (G-CSF), interferon gamma-induced protein 10 (IP-10), and interferon (IFN)-γ have been proposed as poor prognostic factors for COVID-19 patients." (PMID 35098205, 2021). "Indeed, while only one other single-center study showed a beneficial effect of TOC mainly in patients with higher IL-6, our data in a real-world large dataset seems to guide the effective use of TOC in COVID-19." (PMID 33918563, 2021). "IL-6 is thought to play a pivotal role in pathology of COVID-19, considering its highest levels in non-survivors and critically ill patients." (PMID 34912345, 2021). "In response to the first published GWAS of COVID-19, we reported findings that link the ABO signal with a number of clinically actionable targets including coagulation factors (von Willebrand factor [vWF], and Factor VIII [F8]), IL-6, and CD209/DC-SIGN." (PMID 34402426, 2021). "Remarkably, all but one study showed a significant elevation in the level of IL-6 in severe COVID-19 patients compared to non-severe groups." (PMID 34046036, 2021). "In a study of 150 people with confirmed cases of COVID-19, levels of the inflammatory cytokine IL-6 were significantly higher in non-survivors than in survivors of the disease." (PMID 33853637, 2021). "A recent proteomic profiling study pointed to DC-SIGN as a mediator of genetic risk in COVID-19 and finally DC/L-SIGN expression is induced by proinflammatory cytokines such as IL-4, IL-6, IL-10 and IL-13, known to be overexpressed in severe SARS and COVID-19 cases." (PMID 34015061, 2021). "To determine whether traditional biomarkers for inflammation showed the same elevated pattern with disease severity we measured IL-6 and CRP levels in COVID-19 patients across hospital settings." (PMID 33816549, 2021). "Protein-protein docking between COVID-19-Spike and IL6 receptor (IL6R)/IL6/IL6 receptor subunit beta (IL6ST) was simulated to verify whether IL6, the core target identified through our network pharmacology-based approach, was a pathogenic target." (PMID 34731090, 2021). "Knowledge of the kinetics of IL-6 did not offer enhanced predictive value for disease severity in COVID-19 over common investigations such as CRP and vital signs." (PMID 33815405, 2021). "The cytokines interleukin 6 (IL-6), interleukin 1 beta (IL-1β), tumor necrosis factor alpha (TNF-α) and chemokine C–C motif ligand 2 (CCL2), 3 (CCL3), and 5 (CCL5) are upregulated and represent potential targets for treatment of patients with COVID-19." (PMID 33521616, 2021). "An antiviral agent like Remdesivir, as well as immunomodulatory agents such as Tocilizumab (IL-6 inhibitor) and Baaricitinib (JAK inhibitor), and monoclonal antibodies like Bamlanivimab, and Casirivimab/imdevimab can be used to treat patients with COVID-19." (PMID 34058989, 2021). "Patients with COVID-19 had elevated D-dimer, thrombomodulin, and initial factor V elevation followed by decreased factor V and factor VII and elevated IL-6, lactate dehydrogenase, and c-reactive protein, which indicated coagulopathy and possible cytokine storm." (PMID 34829418, 2021). "In turn, it will amplify the inflammatory loop through IL-6-mediated response and inducing more ACE2 expression, which collectively contributes to the occurrence of respiratory and inflammatory syndromes as in COVID-19." (PMID 33503821, 2021).
COVID-19 (continued). "Given the significant dysregulation of key cytokines, such as IL-6 and TNF-α, in patients with COVID-19, we analyzed the RNA-Seq data from these in vitro infection models and compared the data with samples from patients with COVID-19 for similar immune gene expression signatures." (PMID 34731091, 2021). "IL-6 is determined to be involved in the pathology of SARS-CoV-2 and COVID-19." (PMID 33717061, 2021). "COVID-19 patients suffered from headache had significantly higher serum levels of HMGB1, NLRP3, ACE2, and IL-6 than COVID-19 patients without headache, whereas CGRP and IL-10 levels were similar in the groups." (PMID 34384355, 2021). "In this study, we focused on TNFα, IL-1β, and IL-6 as known pro-inflammatory markers of acute inflammatory response, along with CXCL8/IL-8 because of its potent role in the recruitment and activation of neutrophils, commonly elevated in patients with COVID-19." (PMID 34360706, 2021). "On the one hand, post-COVID-19 patients revealed numerous altered parameters of endothelial dysfunction, and subclinical inflammation expressed by elevated levels of CRP, ESR, and IL-6 as well as by a higher total number of pathologically altered inflammatory conditions." (PMID 34722682, 2021). "Also, a signature of the SASP factors IL-6, IL-10, and IP10 in COVID-19 patients appears to predict clinical progression." (PMID 34103349, 2021). "Furthermore, highly elevated serum IL-6, IL-8 and TNF-α in patients with COVID-19 are strong and independent predictors of COVID-19 severity and survival, which suggests the „cytokine storm“ indeed as crucial target for therapy." (PMID 33162939, 2020). "A study of 1,426 patients showed that Interleukin-6 (IL-6) were raised more in patients with severe COVID-19 than non-severe COVID-19 with progressive rise indicating an increased risk of mortality." (PMID 33520910, 2020). "In a study of 77 COVID-19 patients, treatment with IFN-α2b significantly reduced the duration of detectable virus in the upper respiratory tract, and reduced the duration of elevated IL-6 and CRP levels." (PMID 32848776, 2020). "Yet, dynamic changes in IL-6 levels and their prognostic value as an indicator of lung injury in COVID-19 patients have not been fully elucidated." (PMID 32765283, 2020). "Under conditions where no specific medication proves to be efficacious, anti-IL-6 signaling agents are promising for the treatment of COVID-19." (PMID 33384605, 2020). "COVID-19-related severe respiratory failure is characterized in part by increased numbers of neutrophils and lower numbers of lymphocytes (CD4, CD8, and CD19), as well as increased levels of serum IL-6 and C-reactive protein (CRP)." (PMID 33330130, 2020). "In addition to IL-6 and MCP-1, we show that the combinations of these cytokines with IL-1ra and IP-10 were equally good as predictors of COVID-19 severity." (PMID 33303843, 2020). "Cytokine storm is hypercytokinemia that increases the volume of pro-inflammatory cytokines in the serum (e.g. IL-1β, IL-6, IL-12, INF-γ) and chemokines (CXCL10 and CCL2), and is correlated with pulmonary inflammation and extensive lung involvement as seen in COVID-19 patients." (PMID 33205807, 2020). "Due to the importance of IL-6 in SARS-CoV-2 infection, IL-6 antagonists including tocilizumab (NCT04315480) and sarilumab (NCT04327388) are being investigated in clinical trials for treatment of patients with severe COVID-19." (PMID 33156843, 2020). "A systematic review and meta-analysis of eight studies showed elevated IL-6 levels (2.9x) in complicated COVID-19 cases in comparison to noncomplicated COVID-19 cases." (PMID 32775090, 2020). "COVID-19 patients with pneumonia had higher levels of IL-2R, IL-6, and TNF-α than COVID-19 patients without pneumonia." (PMID 32727465, 2020).
COVID-19 (continued). "IL-6 levels were measured by the clinical lab as part of clinical care in 6 of the COVID-19 patients, including 4 with severe disease, though not at matched time points with the research blood collection." (PMID 32706339, 2020). "Others showed that mean IL-6 concentrations were nearly 100 times higher in patients with cytokine release syndrome, 27 times higher in patients with sepsis and 12 times higher in patients with ARDS unrelated to COVID-19." (PMID 33272291, 2020). "Group 1 pediatric patients with COVID-19 who recovered without sequelae exhibited the lowest ADCP activity and had the lowest serum concentrations of IL-6 and TNF, cytokines associated with ARDS, and poor outcome in clinical studies." (PMID 32958614, 2020). "Plasma from severe COVID-19 patients similarly exhibited increased IL-6, IL-10, and MCP-1 levels, but these levels were not as high as those in patients with CRS from other causes." (PMID 32826331, 2020). "Notably, a study of nearly 4,000 patients has found the levels of IL-1, IL-6, and TNF-α to be significantly elevated in the sera of patients suffering from severe COVID-19 as compared to those with mild disease (Wanget al., 2020a)." (PMID 33082935, 2020). "Additionally, we also compared the peak levels of the clinical inflammation parameters C-reactive protein (CRP), IL-6, or ferritin with the expression of activation and inhibitory receptors on CD8+ and CD4+ T cells in COVID-19." (PMID 32983106, 2020). "A retrospective study stated that treatment of COVID-19 patients with IFNα2b reduced the viral load and levels of inflammatory cytokine IL-6 with or without arbidol." (PMID 32784499, 2020). "Indeed, symptomatic COVID-19 patients show elevated levels of several cytokines (TRAIL, MCSF, GRO-α, GCSF, and IL-6, among others) compared to asymptomatic persons." (PMID 32817460, 2020). "IL-6 and LDH were independent predictive parameters for assessing the severity of COVID-19." (PMID 32854750, 2020). "Of note, this model did not recapitulate the increase of systemic IL-6 observed in severe COVID-19 patients in either dose or timepoint." (PMID 32803199, 2020). "IL-6 indeed plays a crucial role into the CRS and IL-6 levels together with C-reactive protein and SaO2/FiO2 ratio would be predictors of rapid clinical deterioration in COVID-19 patients." (PMID 32774170, 2020). "The present review is aimed at overviewing the available experience on the effectiveness and safety of immunomodulatory therapies for the treatment of COVID-19 in SOT recipients, with focus on IL-6-targeted agents in view of the more extensive evidence as compared to other therapeutic groups." (PMID 33110739, 2020). "Nevertheless, the inhibition of the signal transduction mediated by IL-6, the critical STAT3 inducer for the IL-6 amplifier, through binding to both mIL-6Rα and sIL-6Rα is a reasonable approach to consider for treating cytokine storm in COVID-19 patients." (PMID 33014208, 2020). "Anti-IL-6R antibodies such as tocilizumab (NCT04322773) or sarilumab (NCT04359901; NCT04357808), and the anti-IL-6 antibodies clazakizumab (NCT04348500; NCT04381052; NCT04343989; NCT04381052) and olokizumab (NCT04380519) are currently in clinical trials for COVID-19 patients." (PMID 33324210, 2020). "A study used transcription and serum profiling of COVID-19 patients and revealed that SARS-CoV-2 infection induces a high level of chemokines and pro-inflammatory cytokines such as IL6, while very low level of IFN-I or IFN-III resulting limited antiviral ISGs response." (PMID 33362771, 2020). "Elevated levels of proinflammatory cytokines IL-6, IL-8 and TNF-α appear to predict patient survival suggesting that imbalanced immune activity resulting from evolutionary mismatches seems to be the primary driver of COVID-19 morbidity and mortality." (PMID 33235797, 2020).